ERG (ETS transcription factor ERG)
Diseases named in the same sentence as ERG in open-access papers (continued):
Sharing a sentence is not in itself a finding about the gene and the disease.
prostate tumors (continued). "However, in about one-half of prostate tumors, the ETS protein ERG is over-expressed due to a chromosomal rearrangement." (PMID 25885538, 2015). "From a carefully characterized RNA pool of ERG expressing and TMPRSS2-ERG fusion harboring prostate tumors obtained from six radical prostatectomy specimens, cDNA molecules were generated and amplified using 5’ cap-specific forward primers and ERG-specific reverse primers." (PMID 24418414, 2014). "Previous studies have identified TDRD1 as the most differentially expressed gene between ERG-negative and ERG-positive prostate tumors besides ERG." (PMID 23555854, 2013). "In addition to the common fusion with ERG gene, TMPRSS2 is also fused to several other ETS transcription factor genes, such as ETV1, ETV4, and ETV5, in approximately 10% of prostate tumors." (PMID 24133629, 2013). "The most common type of ETS rearrangement, the fusion of androgen-regulated TMPRSS2 with the oncogenic ERG is detected in approximately half of prostate tumors but none of benign glands." (PMID 24098661, 2013). "The highest levels of expression of the 5' gene are found in the ERG-negative prostate tumor samples, although not in all of them." (PMID 21261984, 2011). "It is worth noting that these TMPRSS2-ERG gene rearrangements activate the transcriptional program regulated by YAP1 and that prostate-specific activation of either ERG or YAP1 in mice induces similar transcriptional changes and results in age-related prostate tumors." (PMID 37446279, 2023). "More recent studies have identified that a majority of prostate tumors harbor prostate-specific TMPRSS2 gene and the ERG oncogene (TMPRSS2: ERG) gene fusion which could be used as a stem cell marker with high specificity providing ERG-driven survival advantages." (PMID 35800367, 2022). "It was also recently determined that ERG (and the common TMPRSS2–ERG fusion) activates the transcriptional program regulated by YAP1, and that prostate-specific activation of either ERG or YAP1 in mice induces similar transcriptional changes and results in age-related prostate tumors." (PMID 33297404, 2020). "However, no significant functional GO term was enriched for group-specific genes indicating comparable expression profiles between ERG-positive and ERG-negative prostate tumor types, despite in their differences in their dominant driver genomic alterations." (PMID 30150711, 2018). "Our study highlights potentially actionable genes which may provide opportunities for target therapy of ERG-negative prostate tumors." (PMID 30150711, 2018). "This could indicate that high GS prostate tumors without ERG rearrangement could evolve from an ERG independent pathway." (PMID 29088771, 2017). "Several laboratories, including ours, have shown that ERG expression is detected only in prostate tumor tissue and not in matched controls, consistent with studies showing low/undetectable levels of expression of endogenous ERG protein in prostate epithelial cells." (PMID 25889691, 2015). "In conclusion, a constant presence of ERG is required to maintain high expression of TDRD1 in VCaP cells and the observed co-expression of the two genes in prostate tumors could be explained by a unidirectional activation of TDRD1 through the ERG transcription factor." (PMID 23555854, 2013). "Furthermore, through querying multiple clinical PCa datasets, we found a positive expression correlation between FAM57A and ERG or HNF1B in prostate tumors, but not in adjacent normal prostate tissues, indicating ERG and HNF1B directed transcriptional reprogramming in human PCa tumorigenesis." (PMID 36443337, 2022). "Close inspection of data reveals that in several prostate tumors tested negative for the TMPRSS2:ERG rearrangement, TDRD1 is expressed at high levels despite low ERG expression, suggesting that ERG may not be the only factor which is capable of activating TDRD1 transcription." (PMID 23555854, 2013).
prostate tumors (continued). "Although ERG fusions are frequent, 46% (89 out of 195) of the PCAWG prostate tumors do not show them." (PMID 32636365, 2020). "We inspected methylation of DNA around the TDRD1 transcription start site in prostate tumors, that we had analyzed by MeDIP-Seq, and found this region to be differentially methylated between tumors with and without the TMPRSS2:ERG gene fusion." (PMID 23555854, 2013). "Furthermore, we identified a group of prostate tumors that exhibited marked reduction of ESE3/EHF expression in the absence of alterations of other ETS genes, including ERG." (PMID 31143708, 2019). "Comparison of TMPRSS2-ERG positive and negative primary prostate tumors revealed the co-option of the prostate master transcription factors HOXB13 and FOXA1 and the activation of cis-regulatory elements present in NOTCH pathway-related genes in tumors overexpressing ERG." (PMID 35267426, 2022). "Supporting this hypothesis, PTEN deletion is more common in prostate tumors with TMPRSS2-ERG rearrangements, than in those without, and in mouse models, ERG over-expression results in adenocarcinoma only when accompanied by a second mutation that activates the PI3K/AKT pathway." (PMID 24642271, 2014).
Ewing sarcoma (121 papers, 1994 to 2025). A small round cell tumor that lacks morphologic, immunohistochemical, and electron microscopic evidence of neuroectodermal differentiation. "ERG is one of the most consistently overexpressed oncogenes in malignant prostate cancer and is also implicated in other cancers, including Ewing’s sarcoma and leukaemia." (PMID 39827226, 2025). "Instead, the epigenome of Ewing sarcoma (EWS) cells reflects the regulatory state of genes associated with the DNA binding activity of the fusion oncoproteins EWSR1::FLI1 or EWSR1::ERG." (PMID 38187702, 2023). "Hematopoietic-associated fusions involving ERG also extend to EWSR1-ERG in 5-10% of Ewing’s sarcoma, and ELF4-ERG and FUS-ERG in acute myeloid leukemia." (PMID 37377909, 2023). "The involvement of the ERG in gene translocation (EWS-ERG and TLS/FUS-ERG) and the high expression of ERG are implicated in cancer, including Ewing’s sarcoma and acute myeloid leukemia, in addition to PCa." (PMID 36430730, 2022). "ERG is known to normally regulate endothelial and hematopoietic cell differentiation, and has been implicated as a driver of subsets of Ewing's sarcomas, leukemias and primitive neuroectoderm tumors." (PMID 28465491, 2017). "In this review, we discussed several key sarcoma subtypes characterized by hallmark fusion proteins—such as Ewing sarcoma with EWSR1–FLI1/ERG, epithelioid hemangioendothelioma with WWTR1–CAMTA1/YAP1–TFE1 fusion—and highlighted their clinical implications as targets for therapy." (PMID 40563544, 2025). "Neural crest precursors have also been implicated in neuroblastoma, melanoma, and Ewing sarcoma (a family of bone and soft-tissue cancers with EWS::FLI1 or EWS::ERG rearrangements)." (PMID 41155410, 2025). "This is consistent with the results of the present study that targeting the IGF-IR inhibited the Ewing sarcoma PDOX with the FUS/ERG fusion." (PMID 27286459, 2016). "In Ewing sarcoma and acute myeloid leukaemia, chromosomal translocations result in fusion of ERG with the RNA binding proteins EWS and FUS, respectively, producing chimeric proteins." (PMID 27208692, 2016). "Considering the structural similarities of EWS/FLI and EWS/ERG fusions, it is likely that the two proteins act in order to deregulate similar target genes in Ewing’s sarcoma." (PMID 23329308, 2013). "The same fusion FUS/ERG has also been found in 3 Ewing tumors; it is thus one of the relatively few fusion genes that exert pathogenetic influence in widely disparate neoplastic entities." (PMID 24068373, 2013). "EWS/FLI and EWS/ERG fusions compromise 80–85% and 5–10% of translocations observed in Ewing sarcoma, respectively." (PMID 24704979, 2012). "The androgen-responsive promotor region of the TMPRSS2 gene drives robust expression of ERG, an oncogene that is also frequently involved in chromosomal translocations in Ewing sarcoma, myeloid leukemia and cervical carcinoma." (PMID 21829708, 2011). "Recently, Ewing's tumours have been shown to carry specific hybrid transcripts resulting from the fusion of the EWS gene with FLI-1 or ERG genes." (PMID 7599072, 1995). "The most common fusion gene in Ewing sarcoma are EWSR1::FLI1 (85%) followed by EWSR1::ERG (10%)." (PMID 40666501, 2025). "This FET-ETS fusion between a member of the FET family of genes, usually EWSR1 or FUS, and a member of the ETS (E26 transformation-specific or erythroblast transformation-specific) family of transcription factors, such as FLI1 or ERG, is a marker of Ewing sarcoma." (PMID 40255709, 2025). "In addition to being overexpressed or rearranged in leukemia and Ewing’s sarcoma, ERG plays a central role in PCa tumorigenesis." (PMID 35267426, 2022). "When ERG transcription factors fuse with the EWS Gene, it causes Ewing's sarcoma." (PMID 35361282, 2022). "However, the small molecule ERG/FLI1 inhibitor TK216 tested here has entered a phase 1 study in Ewing sarcoma." (PMID 33218352, 2020).
Ewing sarcoma (continued). "In Ewing sarcoma, ERG fusions result in replacement of the C-terminus of EWS by the DNA-binding domain of ERG resulting in loss of endogenous ERG promoter activity, causing dysregulation of ERG and its target genes." (PMID 27208692, 2016). "Interestingly, the other major EWS fusion partner found in Ewing sarcoma patients is ERG, another gene identified in our screen." (PMID 24827933, 2014). "ERG has also been reported to be overexpressed in Ewing’s sarcomas." (PMID 23555854, 2013). "Ewing sarcoma (ES), the second most common bone cancer in adolescents and young adults (AYA), is caused by a pathognomonic genomic translocation that juxtaposes an N-terminal EWSR1 gene with one of several E26 transformation-specific (ETS) genes (typically FLI1 or ERG)." (PMID 32630797, 2020). "The most frequent gene fusion identified in Ewing sarcoma is EWSR1::FLI1 fusion, and the second most common fusion is EWSR1::ERG." (PMID 40861426, 2025). "Among the Ewing sarcoma cell lines, the expression of KDM6A was similar in cell lines containing EWSR1::ERG compared with those containing EWSR1::FLI1, whereas KDM6B showed higher levels in those with EWSR1::FLI1." (PMID 41085408, 2025). "Even ETS-family transcription factors, including ERG and FLI-1, despite exceptional sensitivity, lack specificity due to their expression in prostate adenocarcinoma, Ewing sarcoma, and other malignancies." (PMID 40666093, 2025). "In summary, we demonstrate that both EWS::FLI1 and EWS::ERG cooperate with P300 to maintain LMNB1 expression and evade senescence-related processes in Ewing sarcoma." (PMID 39367409, 2024). "About 3/4 of Ewing sarcoma and DSRCT tumors have an identical EWS breakpoint motif at Exon 7 (SQQSSSYGQQ-) fused to a specific part of FLI1 (NPSYDSVRRG or-SSLLAYNTSS), ERG (NLPYEPPRRS), FEV (NPVGDGLFKD) or WT1 (SEKPYQCDFK)." (PMID 36900411, 2023). "It was later reported that Ewing sarcoma has more chromosomal translocations, including EWS/FLI fusion, EWS/ERG fusion, EWS/FEV fusion, EWS/ETV1 fusion, EWS/ETV4 fusion, FUS/ERG fusion, FUS/FEV fusion, and FUS/ETV4 fusion." (PMID 36964542, 2023). "Fifteen Ewing sarcoma PDX were established, 13 displayed the EWSR1::FLI1 translocation, one each FUS::ERG and EWSR1::FEV." (PMID 37723198, 2023). "The efficacy of the treatment with YK-4-279 in inducing apoptosis and reducing tumor growth in Ewing’s sarcoma xenograft models and the high homology between FLI1 and other ETS members, in particular ERG, fostered the testing of YK-4-279 in PCa cells." (PMID 35267426, 2022). "Among the 28 Ewing sarcoma patients, the EWS/FLI‐1 and EWS/ERG rearrangements were compared between plasma samples and the respectively paired undecalcified formalin‐fixed paraffin‐embedded (FFPE) tissue samples of 12 Ewing sarcoma patients." (PMID 35486030, 2022). "EWS belongs to the FET family and is often found in Ewing’s sarcoma fused to ETS members, including FLI1 and ERG." (PMID 35267426, 2022). "GGAA repeats are critical regulatory elements in Ewing’s Sarcoma, a disease driven by a translocation of the EWSR1 gene to the DNA binding domain of ERG or FLI1, ERG’s closest homolog in the ETS family." (PMID 34314419, 2021). "For example, Ewing sarcoma translocations involve one of five closely homologous ETS family members (FLI, ERG, FEV, ETV1, and ETV4)." (PMID 34145397, 2021). "The most common fusions in Ewing sarcoma actually occur between EWS and FLI-1 (85%), while the EWS:ERG fusion has a 5–10% occurrence rate." (PMID 27208692, 2016). "Chromosomal rearrangements driving the formation of EWS/ERG and FUS/ERG fusion proteins have been described in a subset of Ewing sarcoma and in acute myeloid leukemia." (PMID 27335598, 2016). "Four EWS/FLI1-rearranged Ewing sarcoma cell lines (A673, EW8, EWS502, and TC71) and one EWS/ERG-rearranged cell line (CADO-ES-1) were included in the screen." (PMID 26337082, 2015).
Ewing sarcoma (continued). "Of the twenty-eight distinct ETS-members in humans, only 5 have been observed in chromosomal rearrangements with EWS in Ewing sarcoma (EWS/FLI, EWS/ERG, EWS/FEV, EWS/ETV1 and EWS/ETV4)." (PMID 24704979, 2012). "Chromosomal rearrangements driving the formation of EWS/ERG and FUS/ERG fusion proteins have been described in a subset of Ewing sarcoma and in acute myeloid leukaemia." (PMID 22140532, 2011). "Among non-endothelial neoplasms, ERG expression has been reported in prostatic adenocarcinomas, Ewing sarcomas, and AML." (PMID 40666093, 2025). "Ewing sarcoma tumouroids preserved characteristic EWSR1 rearrangements with erythroblast transformation-specific (ETS) family of transcription factors such as FLI1, ERG and ETV1." (PMID 41034452, 2025). "In Ewing sarcoma (ES), circulating tumor cells carry the EWS-FLI1/ERG chimeric transcript, which can be isolated from bone barrow or peripheral blood in 19–43% of patients, and this target has long been thought to be a potential clinical biomarker for ES patients." (PMID 40526331, 2025). "Ewing sarcoma is driven by chromosomal rearrangements that create fusion proteins consisting of the ntEWS and the C-terminus of an ETS family transcription factor such as FLI1 or ERG." (PMID 37956771, 2023). "Ewing sarcomas (ES) are rare small round cell sarcomas often affecting children and characterized by gene fusions involving one member of the FET family of genes (usually EWSR1) and a member of the ETS family of transcription factors (usually FLI1 or ERG)." (PMID 37372318, 2023). "Ewing Sarcoma (ES) is a primitive small round cell sarcoma defined by fusions involving members of the FET (predominantly EWSR1 or FUS) and ETS (most commonly including FLI1, ERG, ETV1, ETV4, or FEV) gene families." (PMID 35059992, 2022). "Interestingly, one of these putative off-target genes corresponded to ERG, another member of the ETS family of transcription factors involved in chromosomal translocations in Ewing sarcomas." (PMID 34359682, 2021). "Alternatively, EWSR1 can be fused with ERG, ETV1, E1A-F (alias ETV4) or FEV in Ewing sarcoma." (PMID 29416716, 2018). "For example, Ewing sarcomas with EWSR1-ERG fusions can be detected with the ERG antibody, although this is not specific, as other neoplasms (including vascular tumours, ERG-related myeloproliferative disorders and prostatic adenocarcinomas) express ERG." (PMID 28141799, 2017). "However a case has been described of a patient, in whom two separate Ewing sarcoma/PNET tumours arose after a 56 month remission interval, initially involving a EWS/ERG fusion transcript followed by a EWS/FLI1 fusion." (PMID 22587874, 2012). "Most Ewing sarcomas harbor gene fusions involving the FLI1, ERG, ETV1, ETV4, or FEV gene." (PMID 21789226, 2011). "Ewing sarcoma family of tumors (ESFTs), which includes Ewing sarcoma and primitive neuroectodermal tumors (PNETs), is a group of aggressive malignant neoplasms characterized by small round blue cells and fusion of the ​​​​​​EWSR1 gene with other genes such as FLI1 and ERG." (PMID 40416106, 2025). "It should be noted that SEs are typically absent at the EWSR1, FLI1, and ERG loci in Ewing sarcoma." (PMID 41444391, 2025). "At the same time, YK-4-279 has been shown to inhibit ERG and ETV1 transcription in prostate cancer cells, therefore, it might also be active against Ewing sarcoma cells with commonly and less commonly presented fusion in the tumors with Ewing sarcoma." (PMID 35454895, 2022). "In the 15–20% of Ewing sarcomas that are negative for EWSR1–FLI1, variant fusions between EWSR1 (or rarely FUS gene) and other members of the ETS family occur, most commonly ERG (encoding transcriptional regulator ERG) followed by ETV1, ETV4, FEV and E1AF." (PMID 32295254, 2020).
Ewing sarcoma (continued). "Ewing tumours (ET), including Ewing's sarcoma and peripheral primitive neuroectodermal tumour, are well characterised at the molecular level by a unique chromosomal rearrangement which fuses the EWS gene to one of two closely related ETS proto-oncogenes, FLI-1 or ERG." (PMID 7524604, 1994). "Even though expression levels of wild-type ERG members are not detected in Ewing sarcoma cells, we cannot exclude that EWS-FLI1 may interfere with the potential splicing activity of other members of the ETS family that may be involved in splicing as well, beyond the ERG subfamily proteins." (PMID 34009296, 2021).